SMAD3 (SMAD family member 3)
Diseases named in the same sentence as SMAD3 in open-access papers (continued):
Sharing a sentence is not in itself a finding about the gene and the disease.
liver fibrosis (continued). "The results showed that DIM could inhibit the expression of CCl4-induced TGF-β1 and Smad 2/3, suggesting that DIM could suppress the progression of CCl4-induced liver fibrosis by inhibiting the TGF-β1 and Smad3 signaling pathways." (PMID 36232707, 2022). "In a bile duct ligation animal model of liver fibrosis, Tß4 reduced the expression of many molecules important in the fibrotic pathway including TGF-ß1 (Transforming growth factor-ß1), TGF-ß RII, Smad2, and Smad3." (PMID 36613994, 2022). "However, after HSC transdifferentiation to MFB, the ability of TGF-β1 to induce Smad7 expression decreases, Smad2 and Smad3 are phosphorylated, the TGF-β1/Smads signaling pathway is activated, and ECM is secreted in large amounts, accelerating liver fibrosis." (PMID 35529927, 2022). "Apigenin could alleviate liver fibrosis by inhibiting hepatic stellate cell activation and autophagy via TGF-β1/Smad3 and p38/PPARα pathways." (PMID 33574836, 2021). "We hypothesized that apigenin could alleviate liver fibrosis by inhibiting hepatic stellate cell activation and autophagy via TGF-β1/Smad3 and p38 MAPK/PPARα pathways." (PMID 33574836, 2021). "Interestingly, further study also demonstrated that lnc-SCARNA10 promoted the expression of ATF3 in a TGF-β/SMAD3-dependent manner, revealing a TGF-β/ATF3/lnc-SCARNA10 axis that contributed to liver fibrosis by activating HSCs." (PMID 33311456, 2020). "Mice without Smad3 gene are resistant to radiation-induced skin fibrosis, bleomycin-induced lung fibrosis, and carbon tetrachloride-induced liver fibrosis." (PMID 33101446, 2020). "In addition, we have revealed that ATF3 interacted with SMAD3 to promote the transcription of pro-fibrogenic genes and TGF-β/ATF3/lnc-SCARNA10 formed a positive feedback loop, which contributed to liver fibrosis." (PMID 33311456, 2020). "As crosstalk between SMAD3 and STAT3 in numerous biological functions is well documented, and because TGFβ1 can activate STAT3, which also has a role in liver fibrosis, we hypothesized that STAT3 may contribute to the antifibrotic effects of rottlerin." (PMID 32210801, 2020). "Myricetin also effectively inhibited the expression of TGFβ1, Smad2, phospho-Smad2, Smad3, phospho-Smad3, ERK, phospho-ERK, Akt, and phospho-Akt in the liver of infected mice, suggesting that myricetin attenuated liver fibrosis in mice via modulating TGFβ1 and Akt signaling." (PMID 32373112, 2020). "The evidence supports fibrogenic activity by Smad3 and p38 MAPK in TGF-β1-induced hepatic fibrosis." (PMID 31467486, 2019). "Furthermore, MPOE ameliorated liver fibrosis as evidenced by the reduced expression of desmin, α-smooth muscle actin (α-SMA), transforming growth factor-β1 (TGF-β1), and SMAD3 proteins." (PMID 29849890, 2018). "Thus, to further explore the therapeutic target of ADSCs for treating liver fibrosis, we investigated the expression of key mediators of TGF-β1/SMAD signaling including TGF-β1, SMAD3 and p-SMAD3." (PMID 29258603, 2017). "STAT3 activation accompanies enhanced phospho-Smad3 and CTGF expression in liver fibrosis." (PMID 29152065, 2017). "Considering that TGF-β1/SMAD3 signaling pathway is a key mediator of HSC activation that leads to liver fibrosis, we further used a co-culture system of ADSCs together with HSCs to investigate whether ADSCs could suppress TGF-β1/SMAD3 signaling in HSCs." (PMID 29258603, 2017). "We also found that ADSC transplantation could attenuate liver injury by improving liver function and inhibiting pathological changes of liver fibrosis, as well as through downregulation of TGF-β1 and phosphorylated SMAD3 both in vitro and in vivo." (PMID 29258603, 2017).
liver fibrosis (continued). "Therefore, the TGF-β1-activated Smad3 signaling pathway is critical for the development of hepatic fibrosis, and TGF-β signaling pathways are potential therapeutic targets for liver fibrosis." (PMID 25425284, 2014). "Several researches indicated that salvianolic acid B (SAB) could attenuate liver fibrosis via TGF-β-related signaling pathways, and SAB addition inhibited Smad3 protein expression and its nuclear translocation in hepatic stellate cells." (PMID 24998426, 2014). "Similarly, Smad3—a key downstream effector of TGF-β1 signaling—can be targeted using oligonucleotide inhibitors (e.g., SIS3) or small molecules to block profibrotic signals, as validated in liver fibrosis models." (PMID 40406267, 2025). "It has been demonstrated that SIRT6 inhibits Smad3 activation, a member of the Smad family involved in TGF-β signaling, through H3K9 deacetylation, thereby suppressing the expression of key genes related to liver fibrosis and contributing to fibrosis regression." (PMID 38294557, 2024). "Furthermore, studies highlighting the mechanisms by which SREBP1c regulates hepatic stellate cells and liver fibrosis have revealed that the overexpression of SREBP1c inhibits liver fibrosis in mice by reducing TGF-β levels and signaling through SMAD3 and AKT1, AKT2, and AKT3." (PMID 38256181, 2024). "As DNMT plays an important role in DNA methylation, DNMT inhibition may block the hypermethylation and downregulate related genes (such as PTGIS, PTEN, and Smad2/Smad3), inhibit the activation and proliferation of HSCs, inhibit the expression of α-SMA and COL1A1 in vitro, and delay liver fibrosis." (PMID 37056286, 2023). "Therefore, we can draw the conclusion that apigenin could relieve hepatic fibrosis induced by CCl4 and BDL via downregulating the TGF-β1/Smad3 and p38/PPARα pathways." (PMID 33574836, 2021). "Phosphorylation of the linker region of Smad3 rather than carboxyl terminal motif seems to be dominant in the course of transdifferentiation of HSCs to myofibroblasts, which produce extracellular matrix molecules that contribute to liver fibrosis." (PMID 33396939, 2020). "Our study showed that myricetin suppressed the expression of TGFβ1, phospho-Smad2, phospho-Smad3, phosph-ERK1/2, Akt, phospho-Akt in schistosome-infected mice, revealing that myricetin may reduce liver fibrosis in schistosome-infected mice by inhibiting TGFβ1/Smad/ERK and PI3K/Akt signaling." (PMID 32373112, 2020). "Moreover, Zhang and his colleagues used magnolol to prevent the interaction between SMAD3 and SMAD4 and, thus, could attenuate TGF-β signaling and concanavalin A induced hepatic fibrosis." (PMID 31718044, 2019). "However, our previous work presented that inhibition of Robo1 attenuated hepatic fibrosis through downregulation of the phosphorylation of both Smad2 and Smad3 in HSC independent of TGF-β1." (PMID 29743985, 2018). "Herein, we report the downregulation of p-SMAD3 and TGFβR2 after BM-MSCs administration in rats with liver fibrosis, suggesting the inhibitory effect of BM-MSCs on CCl4-induced fibrosis probably by affecting TGFβ/SMAD signaling pathways through reduction of TGFβR2 and phosphorylation of SMAD3." (PMID 30346985, 2018). "HCW remarkably inhibited phosphorylation of Smad3 and activation of TGF‐β1, suggesting that the inhibitory effects of HCW on hepatic fibrosis might be related to its action on hepatic stellate cells deactivation by controlling the TGF‐β1/Smad3 signalling pathway." (PMID 29654657, 2018). "Our finding that hepcidin inhibits transforming growth factor β1 (TGFβ1)-mediated Smad3 phosphorylation by degrading FPN that is upregulated and responsible for the suppression of Akt signalling in activated HSCs, offers the novel therapeutic approaches to overcome liver fibrosis." (PMID 28004654, 2016).
liver fibrosis (continued). "Although TGFβ1 transcription was reported to be Smad3-dependent, the undetectable decrease of TGFβ1 mRNA expression in NPLC0393 treated liver fibrosis mice might be due to the other signaling pathways besides TGFβ-Smad3, which are also involved in TGFβ1 expression." (PMID 21151953, 2010). "Additionally, multiple signaling pathways, including Src/extracellular regulated protein kinases/drosophila mothers against decapentaplegic homolog 3 (Src/ERK/Smad3), Sirt1/Notch, ferroptosis, and phosphatase and tensin homolog are all involved in the activation of HSCs and hepatic fibrosis." (PMID 39108760, 2024). "Compared with the blank control group, the gene expression of Smad2 and Smad3 in the TGF-β1 experimental group was increased while Smad7 was decreased, indicating that TGF-β/Smad pathway may be involved in the process of excessive activation of HSC and hepatic fibrosis." (PMID 27990439, 2016). "In the context of liver fibrosis, Smad7 acts as a negative feedback regulator, inhibiting the TGF-β1/Smad signaling by preventing the binding of activated TβRI to Smad2/Smad3." (PMID 36474240, 2022). "In mice with induced liver fibrosis, mirtazapine, also a 5-HT2A inhibitor, prevented the Smad3 phosphorylation and TGF-β expression in the liver tissue, although the antibody used to detect Smad3 phosphorylation was not specified." (PMID 39506064, 2025). "The lack of a significant difference in SMAD3 expression after DEN treatment in WT and KO mice may partially explain the absence of changes in liver fibrosis after KLF10 deletion." (PMID 37946098, 2023).
pulmonary fibrosis (190 papers, 2006 to 2026). Chronic progressive interstitial lung disorder characterized by the replacement of the lung tissue by connective tissue, leading to progressive dyspnea, respiratory failure, or right heart failure. "Dysregulation of transforming growth factor-β1 (TGF-β1)/Smad3 signaling pathway is considered to play a central role and is associated with bleomycin-induced pulmonary fibrosis." (PMID 40290659, 2025). "Evidence was found that Smad-3 deficiency attenuates pulmonary fibrosis and that the inhibitor Smad-7 prevents the phosphorylation of Smad-2 and Smad-3, reducing the fibrotic phenomenon." (PMID 38540252, 2024). "We identified over 2,500 O-GlcNAc modified proteins including α-SMA, TIMP1, TIMP3, Smad4, Smad5 and Smad3 have been implicated in pulmonary fibrosis." (PMID 38665916, 2024). "Smads from the cell membrane and nucleus have been identified in fibroblasts after TGF-β1 treatment, and Smad3 deficiency attenuates bleomycin-induced pulmonary fibrosis." (PMID 36949426, 2023). "For example, blockage of TGFβ-mediated SMAD3 phosphorylation prevented bleomycin (BLM)-induced pulmonary fibrosis (PF); however, TGFβ or SMAD3 deletion caused abnormal lung organogenesis and systemic inflammation in mouse models." (PMID 36050716, 2022). "A central role of the TGFβ/Smad signaling pathway in pulmonary fibrosis was demonstrated in mice deficient for Smad3 that were protected from bleomycin induced fibrosis." (PMID 32332792, 2020). "Studies show that the deficiency of Smad3 attenuates bleomycin-induced pulmonary fibrosis in mice and that the inhibitory Smad7 prevents the phosphorylation of Smad2 and Smad3 via activated TGF-β receptors." (PMID 30909462, 2019). "Among the different possibilities suggested, an alteration in the transforming growth factor-β1 (TGF-β1)/Smad3 signalling pathway has been considered to play a central role and is associated with lung fibrosis." (PMID 30134568, 2018). "A substantial body of work has demonstrated that the abnormal expression of the Smad3 gene is an important pathogenic mechanism in diseases such as hepatic, renal, and pulmonary fibrosis." (PMID 28562330, 2017). "Renal interstitial fibrosis, cardiac fibrosis, bleomycin-induced pulmonary fibrosis and dermal fibrosis following irradiation are all attenuated in Smad3-deficient animals." (PMID 29039786, 2017). "This was in contrast to Smad3 deficiency conferring protection from bleomycin-induced lung fibrosis in gp130wt mice." (PMID 22684844, 2012). "Overexpression of TGF-β1 during gestation leads to septal thickening and lung fibrosis, whereas Smad3-deficient mice develop a hypoplastic lung." (PMID 22028866, 2011). "Loss of Smad3 activity has been shown to yield protection from radiation-induced fibrosis 39, bleomycin-induced pulmonary fibrosis 40 and tubulointerstitial fibrosis in the UUO model." (PMID 21984124, 2011). "The data from the bleomycin-induced pulmonary fibrosis animal model also supported the in vitro results, demonstrating that E966-0530-45418 administration significantly decreased the phosphorylation of Smad3 at T179, further reducing fibrosis-associated protein expression." (PMID 39781457, 2025). "And Smad3 deficiency relieved bleomycin- or TGF-β1-induced pulmonary fibrosis in mice." (PMID 37815883, 2023). "Indeed, Smad3-deficient mice exhibited attenuated lung fibrosis induced by bleomycin, and overexpression of Smad3 significantly increased the activity of type I collagen promoter." (PMID 24998426, 2014). "Importantly, gp130-mediated lung fibrosis occurred independently of canonical TGF-β signalling in Smad3-deficient mice, but required mature B lymphocytes and correlated with parenchymal accumulation of B-cell containing foci." (PMID 22684844, 2012).
pulmonary fibrosis (continued). "In the pathogenesis of pulmonary fibrosis, Forkhead box protein O3 (FOXO3) inhibits fibroblast activation and ECM deposition via its interaction with TGF-β1-induced Smad3, thereby attenuating idiopathic pulmonary fibrosis (IPF)." (PMID 40969268, 2025). "MiR-143-5p exemplified this multifunctionality, with reported roles in diabetic retinopathy (via angiogenesis modulation), idiopathic pulmonary fibrosis (through TGF-β/Smad3 signaling), and gastric cancer metastasis (by cytoskeletal remodeling)." (PMID 41372998, 2025). "Under PM2.5 exposure, ER stress triggers apoptosis in lung cells and excessive deposition of extracellular matrix (ECM) through the activation of the TGF-β1/Smad3 signaling pathway, thereby exacerbating pulmonary fibrosis." (PMID 41329539, 2025). "The TGF-β1 signaling pathway significantly affects the regulation of fibroblast activation, in which the key proteins Smad2 and Smad3 are the main downstream regulators that promote TGF-β1-mediated lung fibrosis." (PMID 38895626, 2024). "Other studies have suggested that PD-L1 can promote pulmonary fibrosis through the Smad3/β‐catenin pathway." (PMID 38263193, 2024). "In summary, C-PC alleviates pulmonary fibrosis through the ATF3/Smad3-lncIAPF-HuR signal pathway that targets autophagy." (PMID 39039254, 2024). "This further proves that overexpression of miR-29a can inhibit the TGF-β1/Smad3 signaling pathway and decrease the degree of pulmonary fibrosis in mice." (PMID 39479511, 2024). "Treatment with Br-MSCs, saroglitazar, or their combination that was initiated 14 days after the induction of pulmonary fibrosis significantly (p < 0.05) reduced SMAD-3 gene expression compared to the BLM-G." (PMID 38376539, 2024). "In summary, C-PC alleviates pulmonary fibrosis through the ATF3/Smad3-lncIAPF-HuR signal pathway that targets autophagy and can be a potential drug for treating pulmonary fibrosis." (PMID 39039254, 2024). "In an in vivo silica inhalation-induced model of pulmonary fibrosis, Sirt1 expression was increased following treatment with emodin, which led to Smad3 deacetylation and inhibition of TGF-B/Smad2/3 signaling." (PMID 38474385, 2024). "We have also reported that miR-29b is negatively regulated by Smad3 and that overexpression of miR-29b is able to inhibit Ang II-mediated hypertensive cardiac fibrosis as well as obstructive kidney and lung fibrosis." (PMID 37449045, 2023). "Recent studies have shown that miRNAs can inhibit fibroblast proliferation and pulmonary fibrosis by regulating Smad3." (PMID 37187923, 2023). "GRK2 promoted TGFβ1-induced ECM accumulation by transcriptionally activating Smad3 in lung fibroblasts, the inhibition of which thus attenuated bleomycin-induced lung fibrosis." (PMID 37815883, 2023). "This study demonstrated that the activation of the TGF-β1/SMAD3 signaling pathway was directly responsible for the up-regulation of HDAC3 expression in pulmonary fibrosis." (PMID 37951958, 2023). "Collectively, these data further unveiled that PRXT-mediated inhibition of GRK2 decreased the mRNA and protein expression of Smad3 during pulmonary fibrosis." (PMID 37815883, 2023). "Nonetheless, a recent study has indicated that blocking the TGF-β1/Smad3/ERK/P38 signaling pathway can enhance autophagy to mitigate pulmonary fibrosis." (PMID 37465345, 2023). "For example, dexamethasone attenuates the bleomycin-induced pulmonary fibrosis model via TGF-β, SMAD3, and JAK/STAT pathways, indirectly suggesting that the JAK/STAT pathway is associated with pulmonary fibrosis." (PMID 36671504, 2023). "Treatment with vitamin D prevented lung fibrosis by blocking the TGFβ/Smad3 axis, repressing epithelia-mesenchymal transition (EMT), and restoring mRNA levels of the vitamin D receptor (VDR)." (PMID 36835058, 2023). "According to relevant reports, PFD reduces the infiltration of M2 macrophages and inhibits the activation of TGF-β1/Smad3 signalling to improve radiation-induced lung fibrosis." (PMID 37954024, 2023).